F2RL2 (coagulation factor II thrombin receptor like 2)
Description:
Receptor for activated thrombin coupled to G proteins that stimulate phosphoinositide hydrolysis.
Synonyms: PAR-3; PAR3
Tractability: Small molecule: it belongs to a druggable protein family. Antibody: its Gene Ontology location is reachable by antibodies, with high confidence; UniProt places it where antibodies can reach, with medium confidence; UniProt predicts a signal peptide or a membrane-spanning region. PROTAC: ubiquitination databases record sites on it.
Target class: Protease-activated receptor; Membrane receptor; Peptide receptor (family A GPCR); Family A G protein-coupled receptor
Gene: Protein-coding gene on chromosome 5 (76,615,482 to 76,623,413, reverse strand). Ensembl gene ENSG00000164220.
Subcellular location: Cell membrane
Pathways (Reactome):
Signal Transduction: G alpha (q) signalling events; Peptide ligand-binding receptors
Hemostasis: Thrombin signalling through proteinase activated receptors (PARs)
Gene Ontology:
Molecular function: protein binding; G protein-coupled receptor activity; phosphatidylinositol-4,5-bisphosphate phospholipase C activity; thrombin-activated receptor activity; proteinase-activated receptor activity; receptor ligand activity
Biological process: blood coagulation; G protein-coupled receptor signaling pathway; platelet activation; response to wounding; thrombin-activated receptor signaling pathway
Cellular component: protein-containing complex; extracellular region; plasma membrane; apical plasma membrane; membrane
Genetic constraint (gnomAD): Loss-of-function variants: 6 observed, 8.45 expected, observed/expected ratio (o/e) 0.71, 90% interval 0.39 to 1.39. That is too few expected variants to judge how well the gene tolerates losing a copy. Missense variants: 408 observed, 474.53 expected, observed/expected ratio (o/e) 0.86, 90% interval 0.79 to 0.93. Synonymous variants: 166 observed, 181.9 expected, observed/expected ratio (o/e) 0.91, 90% interval 0.8 to 1.04.
Homologues: Orthologues: chimpanzee F2RL2 (99% identical), macaque F2RL2 (98% identical), dog F2RL2 (88% identical), pig F2RL2 (87% identical), mouse F2rl2 (70% identical), rat F2rl2 (67% identical), guinea pig F2RL2 (58% identical), tropical clawed frog f2rl2 (49% identical), zebrafish F2RL2 (35% identical), zebrafish f2rl2 (31% identical). Paralogues in human: F2RL1 (31% identical), F2RL3 (30% identical), F2R (30% identical), P2RY8 (26% identical), GPR17 (23% identical), LPAR6 (23% identical), LPAR4 (22% identical), CYSLTR1 (22% identical), CYSLTR2 (22% identical), GPR18 (21% identical), GPR4 (21% identical), P2RY10 (20% identical), and 4 more.
Diseases named in the same sentence as F2RL2 in open-access papers:
F2RL2 is named in the same sentence as 26 diseases in open-access papers, as found by Europe PMC text mining. Sharing a sentence is not in itself a finding about the gene and the disease. The quoted sentences say what the papers report.
glioma (4 papers, 2020 to 2024). A benign or malignant brain and spinal cord tumor that arises from glial cells (astrocytes, oligodendrocytes, ependymal cells). "Many other studies have shown that F2RL2 is a biomarker for a variety of tumors, such as colon adenocarcinoma and glioma." (PMID 38245717, 2024). "It has been reported as a prognostic marker for oral squamous cell carcinoma, metastatic breast cancer, pancreatic cancer, and glioma, and down-regulated F2RL2 expression has been detected in rectal cancer." (PMID 36105107, 2022). "Compared with CLCNKA and LOXL4, F2RL2 was specifically applied in all grades of primary glioma, revealing its prognostic role in primary glioma." (PMID 32725165, 2020). "F2RL2 has been reported to be a prognostic marker for glioma and breast cancer." (PMID 35637633, 2022). "F2Rl2 is a G-protein-coupled receptor (GPCR) encoding the protease-activated receptor-3 (PAR3), which plays a clear role in inflammatory reactions and immune responses, and PAR3 can regulate the tumorigenesis and metastasis in many kinds of tumors including glioma." (PMID 32725165, 2020). "Thus, we supposed that the roles of F2Rl2 in primary glioma might be related to PAR3 by inflammatory reactions." (PMID 32725165, 2020). "Additionally, we also identified three novel prognostic biomarkers (F2RL2, CLCNKA and LOXL4) for glioma patients in silico." (PMID 32725165, 2020). "Besides other eight reported biomarkers of glioma, we found that F2RL2, CLCNKA and LOXL4 were first identified as prognostic biomarkers for glioma." (PMID 32725165, 2020). "Additionally, this in silico study also identifies three novel prognostic biomarkers (F2RL2, CLCNKA and LOXL4) for glioma patients." (PMID 32725165, 2020). "Finally, the 11 prognostic SRGs in the final multivariate model were validated by the CGGA data and we found three novel prognostic biomarkers (F2RL2, CLCNKA and LOXL4) for glioma that have not been reported before." (PMID 32725165, 2020). "F2RL2, CLCNKA and LOXL4 are novel prognostic biomarkers for glioma which have not reported before." (PMID 32725165, 2020).
breast carcinoma (3 papers, 2022 to 2025). "In breast cancer, F2RL2 promotes tumor growth and metastasis by activating the thrombin signaling pathway, whereas in ovarian cancer, it accelerates tumor progression by modulating immune evasion mechanisms, such as modulating immune cell infiltration." (PMID 40784724, 2025). "For example, F2RL2 was identified as a prominent gene in both breast cancer and ovarian cancer." (PMID 40784724, 2025). "It has been revealed that F2RL2 can promote the tumorigenesis and immigration of breast cancer, indicating that these genes may serve as innovative biomarkers for early ESCC diagnosis." (PMID 37313409, 2023).
colon adenocarcinoma (2 papers, 2024 to 2025). "Elevated expression of F2RL2 correlates with reduced risk and longer survival in colon adenocarcinoma." (PMID 40777024, 2025).
colorectal cancer (2 papers, 2022 to 2023). A primary or metastatic malignant neoplasm that affects the colon or rectum. "Previous studies have reported that F2RL2 can be targeted by miR-429 and miR-483-3p in colorectal cancer and anaplastic thyroid cancer, respectively." (PMID 36540097, 2022). "Previous researches verified that F2RL2 can be targeted by miR-429 and miR-483-3p in colorectal cancer and anaplastic thyroid cancer." (PMID 36540097, 2022). "Moreover, F2RL2 was identified significantly correlated with initiation and progression of colorectal cancer." (PMID 37313409, 2023).
myocardial infarction (2 papers, 2022 to 2025). Gross necrosis of the myocardium, as a result of interruption of the blood supply to the area, as in coronary thrombosis. "This study is aimed at effectively investigating the role of coagulation factor II thrombin receptor like 2 (F2RL2) in myocardial infarction (MI) as well as the upstream regulatory miRNA and lncRNA." (PMID 36540097, 2022).
ovarian carcinoma (2 papers, 2022 to 2025). A malignant neoplasm originating from the surface ovarian epithelium. "Besides, F2RL2 expression is associated with the poor prognosis of ovarian cancer patients." (PMID 36540097, 2022).
cholangiocarcinoma (1 paper, 2025). A carcinoma that arises from the intrahepatic biliary tree (intrahepatic cholangiocarcinoma) or from the junction, or adjacent to the junction, of the right and left hepatic ducts (hilar cholangiocarcinoma). "This revealed tumor‐specific potential markers, several of which have been previously implicated in tumor biology (e.g., F2RL2 in gynecological cancers, DHCR24 and RAG1 in thymic carcinoma, PTGDS in cholangiocarcinoma)." (PMID 40784724, 2025).
Hepatitis (1 paper, 2022). Inflammation of the liver. "In addition, most of these genes have a risk coefficient greater than 0 (AC008271.1, C11orf53, F2RL2, GBP5, LUCAT1, RP11‐149I23.3, RP11‐383 J24.1 and SLC35G2), except for CASP8 and RP11‐114B7.6, suggesting that these genes are adverse prognostic factors in hepatitis‐positive HCC patients." (PMID 35637633, 2022).
psoriasis (1 paper, 2022). An autoimmune condition characterized by red, well-delineated plaques with silvery scales that are usually on the extensor surfaces and scalp. "Further studies confirming the functional implication of IQGAP2/F2RL2 in psoriasis and the response to anti-TNF agents are warranted." (PMID 36059983, 2022).
cancer (6 papers, 2023 to 2025). A tumor composed of atypical neoplastic, often pleomorphic cells that invade other tissues. "In this study, the ARGs signature consisted of four genes (RAMP1, FOXL1, SLCO1B3, and F2RL2) that have previously been documented to be closely linked with cancer." (PMID 40165896, 2025). "CELSR3, GPR25, EDNRB, and F2RL2 are significantly associated with patients’ survival in four cancers each, with an equal prevalence for lower and higher survival." (PMID 38723607, 2024). "While only 1–2 genes (e.g., F2RL2) were shared across multiple cancers, their roles varied with the tumor microenvironment." (PMID 40784724, 2025). "Analysis of large cancer datasets reveals that F2RL1 expression is among the highest in colon adenocarcinoma compared to numerous other cancer types, and significantly higher than other PAR family members (F2R/PAR1, F2RL2/PAR3, F2RL3/PAR4) within CRC tissues." (PMID 41002416, 2025). "Besides, several genes (including MAMDC2, F2RL2, and KCNMA1) were enrolled as biomarker for the prognosis of varying cancers." (PMID 37313409, 2023).
tumor (4 papers, 2022 to 2025). "Consistently, our IHC results revealed significantly elevated protein levels of F2RL2 in ESCC tissues compared to adjacent non-tumor tissues, and elevated F2RL2 expression was correlated with unfavorable prognosis." (PMID 40165896, 2025). "Our analysis revealed that TIMP1 was predominantly expressed across various cell types, particularly stromal cells, while MMP10 and F2RL2 exhibited low expression levels in both non-tumor and tumor cells." (PMID 40777024, 2025). "The protein level of F2RL2 in ESCC tissues was significantly higher than that in adjacent non-tumor tissues." (PMID 40165896, 2025). "The CD1A, CD1B, GRP, SERPINE1, and F2RL2 genes were highly expressed in tumor tissue." (PMID 36221049, 2022).
F2RL2 also shares sentences with these, for which no sentence is quoted: Alzheimer disease (1 paper); anaplastic thyroid cancer (1); brain diseases (1); colon cancer (1); gynecological cancers (1); legionellosis (1); lung carcinoma (1); Obesity (1); oral squamous cell carcinoma (1); pancreatic cancer (1); prostatic cancer (1); rectal cancer (1); skin cancer (1); thymic carcinoma (1); thyroid cancer (1).